ROR2 (ROR family WNT receptor 2)
Diseases named in the same sentence as ROR2 in open-access papers (continued):
Sharing a sentence is not in itself a finding about the gene and the disease.
cancer (97 papers, 2009 to 2026). A tumor composed of atypical neoplastic, often pleomorphic cells that invade other tissues. "Hypermethylation of the HADH gene has been identified as one mechanism underlying its downregulation in CRC, where it modulates cancer cell proliferation through the Wnt/β-catenin and Wnt/ROR2/DVL2 signaling pathways." (PMID 41583431, 2025). "ROR2 is implicated in carcinogenesis by enhancing various cancer-related features, including cell proliferation, apoptosis, migration, invasion, EMT, and in vivo tumor growth." (PMID 38632356, 2024). "Our findings that elevated ROR2 expression associated with worse outcome in HER2 + patients with minimal post-treatment residual cancer burden (RCB-0/I) was based on a small number of events." (PMID 37029329, 2023). "ROR2 expression has also been found in primary and metastatic OC tumors and linked to cancer cell adhesion, proliferation, EMT, and chemoresistance." (PMID 37400436, 2023). "WNT5A expression is associated with several cancers, resulting in constitutive activation of ROR2-mediated signaling and contributing to tumor progression (7, –9)." (PMID 37722040, 2023). "Given the association of ROR2 with cancer and its relatively restricted expression in the cell surface of tumor cells, targeting ROR2 (particularly using monoclonal antibodies) is being evaluated as a new therapy against cancer." (PMID 36127680, 2022). "AXL receptor tyrosine kinase (AXL) and receptor tyrosine kinase like orphan receptor 2 (ROR2) are cancer-associated antigens." (PMID 33482842, 2021). "Ror2 plays significant roles during early embryonic development in several types of tissues, and Ror2 is a potential therapeutic target in cancer due to its association with cancer formation." (PMID 33323370, 2021). "Along with our findings, high ROR2-expressing UTUC is associated with aggressive cancer characteristics and worse outcomes." (PMID 34440262, 2021). "The clinical observations that ROR1 and ROR2 are associated with disease progression and metastasis in many cancer patients have inspired researchers to investigate the role of both co-receptors in the underlying cellular processes." (PMID 33445713, 2021). "Taken together, the data imply that both ROR1 and ROR2 are associated with highly malignant cancer cell phenotypes characterized by high motility and aggressiveness." (PMID 33445713, 2021). "Still, both ROR1 and ROR2 are overexpressed in many cancer entities and studies have linked overactive WNT/ROR signaling to key tumorigenic processes such as cell survival, proliferation, and invasiveness." (PMID 33445713, 2021). "ROR2 has a more general role in cellular proliferation and migration, and this role has been implicated in several cancers of various tissue types." (PMID 29940858, 2018). "It is possible that in our experiments on an immortal cancer cell line, the cellular and genetic context was significantly different and that the loss of ROR2 resulted in the activation of different signalling pathways." (PMID 27440078, 2016). "Moreover, elevated ROR2 levels in cancer patients are associated with unfavorable clinical outcomes, including lower overall survival rates, higher histological grades, worse disease-free survival, and advanced metastatic stages." (PMID 38632356, 2024). "Thus, “drugging” ROR2 would provide the opportunity for specifically targeting invasive cells associated with the dissemination of cancer." (PMID 36127680, 2022). "However, the observation that certain ROR2-overexpressing cancers become susceptible to PARP inhibition paves the way for a new approach for treating such ROR2-positive tumors." (PMID 34911552, 2021). "High ROR2 expression is usually linked to the increased migration and invasiveness of cancer cells." (PMID 31382410, 2019). "Moreover, expression of Ror2 also showed significant associations with both recurrence-free survival and cancer-specific survival." (PMID 25542006, 2014).
cancer (continued). "In the human digestive tract, there is a growing body of evidence that mutations or epigenetic changes of Wnt5a and Ror2 are associated with malformations and cancers, although their functions in regulating the adult stem cells remain almost unknown." (PMID 25211363, 2014). "While ongoing research has begun to reveal the pro-tumorigenic functions of ROR1 and ROR2 in cancer, the mechanisms underlying their regulation and their context-dependent functionality in the distinct tumor entities, which has caused conflicting observations, are still largely unknown." (PMID 33445713, 2021). "Furthermore, we note that Ror2 overexpression has been linked to cancer development." (PMID 30729180, 2019). "While these observations were made in a limited sample set, they align with our preclinical findings, supporting a potential tumor-progressive role of the ROR2-YAP/TEAD axis in patients with HER2-positive cancers characterized by trastuzumab resistance." (PMID 40542295, 2025). "For example, monoclonal antibodies have recently been developed to target the ROR1/ROR2 heterodimer and ROR2 homodimer in cancer." (PMID 40667148, 2025). "Future investigations should focus on expanding the sample size, incorporating functional analyses, and evaluating the prognostic, and therapeutic value of ROR2-YAP/TEAD signaling in trastuzumab-resistant HER2-positive cancers." (PMID 40542295, 2025). "YAP inhibition via verteporfin shows potential in reducing oncogenic properties and overcoming immune evasion in HR cells, providing a strong rationale for further exploration of the ROR2-YAP/TEAD axis as a therapeutic target for HR HER2-positive cancers." (PMID 40542295, 2025). "The identified upregulation here of both Wnt5a and its co-receptor ROR2 is particularly intriguing due to their dual and often contradictory roles in cancer." (PMID 41007281, 2025). "Targeting the ROR2-YAP/TEAD axis presents a promising therapeutic approach to overcome trastuzumab resistance in HER2-positive cancers, offering a potential strategy for enhancing treatment efficacy and improving clinical outcomes." (PMID 40542295, 2025). "In conclusion, CAFs regulate the symmetric division of OCSCs as well as the dedifferentiation of bulk cancer cells to OCSCs through secretion of Wnt5a, which acts via its co-receptor ROR2, on neighboring cancer cells, phosphorylating PKC and CREB1." (PMID 38191909, 2024). "ROR1 and ROR2, involved in developmental processes and cancer progression, primarily modulate the Wnt signaling and JAK/STAT pathways." (PMID 39138146, 2024). "We find that ROR2 is localized on the plasma membrane and on long filopodia of CAFs, which form a dense filopodia network interacting with the cancer cells." (PMID 37722040, 2023). "Wnt5a, which interacts with RoR2 physically and functionally, has been demonstrated to be related to the growth of many different cancers." (PMID 36923505, 2023). "Monoclonal antibodies targeting ROR1 and ROR2, which are oncoembryonic antigens found on cancer cells and promote movement, survival, and proliferation, are also being studied." (PMID 37097545, 2023). "ROR2-v1 was the predominantly expressed isoform in both non-diseased tissues and among all 33 different tumour types profiled by TCGA and hence this is the isoform that should primarily be examined when delineating the role of ROR2 in cancer." (PMID 36289823, 2022). "Enhanced expression of Ror1 and/or Ror2 in cancer cells can promote their proliferation, migration, invasion, survival or chemoresistance through activation of Rho-family GTPases, c-Src, MAP kinases or Akt in Wnt5a-dependent and/or -independent manners." (PMID 35493090, 2022). "In several other tumor types including cancers from the breast, prostate, and ovary among others, ROR2 promotes cancer." (PMID 36127680, 2022). "ROR2 expression is strongly downregulated after birth but was shown to express aberrantly in cancer as well as in other pathological conditions in the adult." (PMID 36127680, 2022).
cancer (continued). "So, further elucidation of the role of ROR2 in “phenotype switching” will contribute to a better understanding of this process and will provide interesting new alternatives for cancer treatment." (PMID 36127680, 2022). "Numerous studies have reported cytoplasmic ROR1 expression and contradictory findings for the role of ROR2 in cancer; hence we sought to determine the functionally significant transcript variant that ought to be examined." (PMID 36289823, 2022). "In cancer, ROR2 stimulates proliferation, survival, migration, and metastasis, and is associated with more aggressive tumor stages." (PMID 35260073, 2022). "Receptor tyrosine kinase-like orphan receptor 2 (ROR2) is a receptor for the Wnt5a ligand that was shown to play a dual role in cancer." (PMID 36127680, 2022). "In cancer, ROR2 possesses a dual role by either suppressing or promoting tumor progression in different tumor types." (PMID 36127680, 2022). "This suggested that even though the expression of ROCK1 had initially not been found to differ between cells transfected with empty vector or pROR2, the ROR2-induced increase in cancer cell invasiveness involved both, ROCK1 and ROCK2." (PMID 34911552, 2021). "Receptor tyrosine kinase-like orphan receptor 2 (ROR2) is a Wnt5a receptor aberrantly expressed in cancer that was shown to either suppress or promote carcinogenesis in different tumor types." (PMID 34774050, 2021). "In multivariate analysis, after adjusting for standard clinicopathological features, ROR2 expression status was an independent prognosticator of cancer-specific survival and metastasis-free survival in UTUC and UBUC (all p < 0.01)." (PMID 34440262, 2021). "While most studies identified ROR1 as an oncogene, the role of ROR2 in cancer is less clear and has been controversially discussed." (PMID 33445713, 2021). "Further in vitro studies have indeed confirmed higher expression of typical epithelial factors (e.g., CK19, CDH1) and lower expression of mesenchymal factors (e.g., SNAI2, ZEB1, VIM) after ROR1 or ROR2 knockdown in cancer cells." (PMID 33445713, 2021). "Receptor tyrosine kinase-like orphan receptor 1 (ROR1) and 2 (ROR2) are receptors for the Wnt5a ligand that have been proposed as potential high-value targets for cancer therapy." (PMID 34774050, 2021). "While different approaches are currently being developed for targeting ROR1, research on ROR2 with regard to its use in cancer therapy is still in its infancy." (PMID 33445713, 2021). "In both scenarios, there is very limited information regarding the mechanisms by which ROR2 regulates these processes in cancer." (PMID 34774050, 2021). "ROR2 has been proposed as a therapeutic target in cancer and antibody-based therapeutic tools have been already developed." (PMID 34774050, 2021). "We found that high ROR2 expression tumors were significantly associated with muscle-invasive or lymph node metastatic UTUC and a high cancer death rate." (PMID 34440262, 2021). "Owing to these interesting features, including its significance in development and potential for cancer therapy, Ror2 has attracted considerable attention." (PMID 33323370, 2021). "Compared to ROR1, ROR2 has been less investigated as a cancer drug target, likely due to its complex dual role in carcinogenesis." (PMID 34763666, 2021). "Several studies have reported the upregulation of ROR1 or ROR2 in chemoresistant cancer cell lines as well as in patient-derived tissues after chemo- or targeted therapy." (PMID 33445713, 2021). "The receptor tyrosine kinase ROR2 is an important regulator in human cancers, serving as a tumor activator or an oncogene." (PMID 32614787, 2020). "ROR2 is thought to be a crucial regulator in human cancers, serving as a tumor-inducible protein and an oncogene." (PMID 32614787, 2020). "ROR2 plays a dual role in cancer, as either tumor suppressor or activator depending on the affected tissue." (PMID 30655605, 2019).
cancer (continued). "Bridging the gap between in vitro and in vivo, the platform presented here is useful in screening compounds that block autophosphorylation of Ror2 and other Tyr kinases for cancer therapeutics." (PMID 30729180, 2019). "As an identified oncogene, ROR2 has been described as a candidate for targeted therapy for several cancers, and the search for an effective ROR2 inhibitor is currently underway." (PMID 29940858, 2018). "ROR2 was found to be highly expressed in a variety of cancers, and in the majority of those, ROR2 expression was associated with more aggressive disease states, consistent with its involvement in WNT signaling." (PMID 29325228, 2018). "Here, we focused on human ROR2 and the identification of novel mAbs and ADCs against this promising cancer cell target." (PMID 30450096, 2018). "The discovery strategy entailed immunization of transgenic mice with the cancer antigen ROR2, harboring transgenic IgH and IgL chain gene loci with limited number of fully human V, D, and J gene segments." (PMID 30450096, 2018). "It was the objective of this study to discover antibodies specifically targeting the TAA ROR2 with high internalization rates, eventually leading to potent cancer cell killing with anti-ROR2-antibody based ADCs." (PMID 30450096, 2018). "Downregulating the expression of ROR2 significantly suppressed cancer cell migration and invasion, and overexpression of ROR2 in parental cell line promoted the cell ability of invasion." (PMID 29108281, 2017). "Although previous efforts identified CD55 as a prognostic marker in several cancers, our data provide mechanistic insight into a bifurcating signaling network that regulates self-renewal via ROR2/JNK signaling and cisplatin resistance via LCK signaling." (PMID 28838952, 2017). "These conflicting reports have raised questions as to the role ROR2 plays in cancer and presents the possibility that the downstream effects of ROR2 are dependent on other Wnt genes and the cellular context of the cancer itself." (PMID 27440078, 2016). "As the exact signalling consequences of these ROR2 interactions are as yet uncertain, it is possible that ROR2 downregulation resulted in different signalling cascades in in vivo mice and in immortal cancer cells." (PMID 27440078, 2016). "Wnt5a activated through Ror2 regulates the expression of matrix metalloproteases (MMPs) which are the most common target genes related to cancer invasion." (PMID 26608372, 2016). "Both ROR1 and ROR2 have been linked to the β-catenin independent Wnt signalling pathway, but little is known about the downstream targets of ROR1 and ROR2 in cancer, and their effect on the β-catenin dependent Wnt signalling pathway." (PMID 26515598, 2015). "ROR2 appears to possess dual roles and can act to suppress or promote carcinogenesis in different cancer tissues." (PMID 26259918, 2015). "ROR2 is a member of the receptor tyrosine kinase superfamily and its overexpression has been reported in many human cancers over the last few years, though little has been reported as to the downstream signalling cascade." (PMID 26515598, 2015). "Cell migration and invasion were also suppressed in Wnt5a-, Ror1-, Ror2-, or Fz2-depleted HeLaS3 and A549 cells, suggesting that both cell proliferation and migration capabilities of these cancer cells depend on Wnt5a signaling through its receptors." (PMID 25622531, 2015). "ROR2’s biological functions are mainly in early embryonic development, although recent evidence has shown ROR2 expression to be up-regulated in many cancers, making ROR2 a potential drug target." (PMID 26589967, 2015). "Many studies have attempted to determine the prognostic values of ROR2 and Wnt5a in various cancers." (PMID 26305508, 2015). "The aberrant expression of Ror2 has been shown to serve in a tumor promoting role in variety of cancers, including RCC." (PMID 25542006, 2014).
cancer (continued). "These lines of evidence suggest that the role of ROR2 in cancer is complex and that it can either promote or suppress tumour formation, depending on tumour type and molecular context." (PMID 20591152, 2010). "The relationship between cancer and ROR2 has been investigated, but the results have been unclear." (PMID 37814183, 2024). "In the case of ROR2, no mutation was detected in cancers, however, a study focused on 21 patients with short stature, identified 10 missense, one nonsense and one frameshift mutation." (PMID 39138146, 2024). "Besides that, ROR2 appears to play a dual role as a tumour suppressor or activator in certain types of cancer." (PMID 37749917, 2023). "Thus, our analyses demonstrate that tumor EVs carrying either ROR1 or ROR2 support an aggressive phenotype in cancer cells even after efficiently inhibiting their uptake into target cells." (PMID 37430307, 2023). "Although Ror1 and Ror2 play important roles during embryonic development, their upregulated expression contributes to cancer progression by regulating the proliferation, migration, invasion, survival, and chemoresistance of cancer cells." (PMID 37703992, 2023). "When receptor ROR2 binds to a small amount of WNT5A, it could slow down the secretion of cytokines and chemokines from cancer cells, regulating the mutated LRSAM1." (PMID 35164166, 2022). "Contradictory roles for ROR2 have been reported in various cancers." (PMID 36289823, 2022). "Although ROR2 has been involved in diverse processes in cancer, the implicated mechanisms have not been fully elucidated." (PMID 34774050, 2021). "In line with the rather mesenchymal, highly motile phenotype typically observed in basal-like cancer cells, ROR2 overexpression resulted in apparent defects in cell-cell-contacts with large gaps in confluent cell layers and membrane ruffles at cellular junctions." (PMID 34911552, 2021). "ROR1 and ROR2 are known to overexpress in the tumor tissues from several types of cancer patients." (PMID 34319035, 2021). "Likewise, the expression of several cell cycle-related genes including CDK1/2/4, CCNE1, CCND1/2, PCNA, and MKI67 has been described to be regulated by ROR2 in these cancer entities." (PMID 33445713, 2021). "Compared with ROR1, the expression profile of ROR2 in cancer is much more heterogeneous." (PMID 33445713, 2021). "The Wnt signalling receptor ROR2 has been identified as a possible therapeutic target in numerous cancers; however, its exact role remains unclear." (PMID 33494187, 2021). "Interestingly, ROR2 possesses dual roles in cancer and can act to either suppress or promote carcinogenesis in different cancers." (PMID 34774050, 2021). "However, we considered worth pursuing ROR2 investigation given the reagent availability and that it has been previously involved in proliferation, migration and invasion of several cancer cells." (PMID 33178184, 2020). "ROR1 and ROR2 are receptor tyrosine kinases with altered expression in a range of cancers." (PMID 32807831, 2020). "Additionally, ROR2 was recently found to be expressed in multiple myeloma, where it mediates the interaction between cancer cells and the bone marrow microenvironment niche." (PMID 31382410, 2019). "Deregulated WNT5A/ROR2 signaling appears to be of great importance in cancer." (PMID 29930766, 2018). "Using this strategy, we identified and validated 12 fully human, monoclonal anti-human ROR2 antibodies with nanomolar affinities that are highly potent as ADCs and could be promising candidates for the therapy of human cancer." (PMID 30450096, 2018).